LEP (leptin)
Diseases named in the same sentence as LEP in open-access papers (continued):
Sharing a sentence is not in itself a finding about the gene and the disease.
Anorexia (continued). "The role of 5-HT and its receptors in cisplatin-induced anorexia was investigated in four studies; inflammatory cytokines and WBCs were also studied in four studies each; the roles of ghrelin and leptin in cisplatin-induced anorexia were assessed in five and two studies, respectively." (PMID 35215322, 2022). "Leptin levels usually increase during an infection and this increase could be related to the anorexia induced during a parasitic infection." (PMID 36140716, 2022). "However, in the later stages of LIF-induced anorexia, food intake returns to basal levels as serum and adipose leptin expression decreases and hypothalamic STAT3 phosphorylation activation is reduced." (PMID 35740622, 2022). "As laparoscopy has been shown to reduce the tissue trauma and inflammatory response effectively after surgery, this might also reduce the postoperative inflammatory response, leptin secretion, and anorexia." (PMID 34827598, 2021). "The sample size was relatively small, and further prospective studies on a larger sample size might be necessary to confirm the relations between leptin and anorexia." (PMID 34827598, 2021). "Laparoscopy could, therefore, promote a better nutritional status in a subgroup of patients by lowering serum leptin levels after operation, and reducing postoperative anorexia compared with open surgery." (PMID 34827598, 2021). "In particular, a massive release of cytokines can trigger effects that mimic the leptin hormonal signaling and suppress the ghrelin and neuropeptide Y signaling, without a compensatory response, thus inducing the sustained anorexia frequently observed in cancer patients." (PMID 34055649, 2021). "Lastly, leptin secretion decreases, corresponding to anorexia." (PMID 33329438, 2020). "IL-1β decreases food intake and body weight via leptin activation in adipose tissue, but it is also able to induce anorexia independently from leptin, by induction of the melanocortin system in the hypothalamus (the main area in the brain regulating feeding behavior and body weight)." (PMID 33202621, 2020). "In a separation-based model of anorexia, refeeding was associated with an increase in fat mass without restoration of plasma leptin." (PMID 33202638, 2020). "This may be mediated, at least in part, by leptin, as women with anorexia have also been demonstrated to have lower leptin concentration than do controls." (PMID 31220230, 2019). "Leptin is an additional hormone that has been involved in the pathogenesis of anorexia of aging." (PMID 26828516, 2016). "Consequently, it seems necessary to consider initial BMI levels and symptom severity before initiating the treatment of anorexia with leptin, and to closely monitor psychic factors during such a treatment." (PMID 28030575, 2016). "As such, it is plausible that the 3-month dietary intervention promoted a state of dietary anorexia that promoted a rapid decline in leptin that may have exceeded the capacity of changes in fat tissue on leptin secretion." (PMID 28050279, 2016). "Cytokine overproduction and particularly leptin by mesenteric fat could lead to anorexia, another feature present in CD." (PMID 24877092, 2014). "Meanwhile, GLP-1, PYY, ghrelin, and leptin are known as readouts for anorexia/cachexia." (PMID 24963216, 2014). "The proinflammatory nature of leptin has been noted in several studies, with intravenous injection of endotoxin inducing a sudden rise in leptin levels, as well as endotoxin-induced fever and anorexia in rats, again inducing an increase in leptin levels as part of the inflammatory response." (PMID 24455420, 2013). "Human studies in cancer patients have shown that leptin levels are not elevated during weight loss demonstrating that the hormone leptin is not involved in the initiation of anorexia in this population." (PMID 24177709, 2013).
Anorexia (continued). "Initially, it was proposed that activation of mTOR signaling in the hypothalamus promoted anorexia; in fact it was demonstrated that short-term central administration of anorectic factors, such as leucine, leptin, CNTF, α-lipoic acid or BMP7 increase hypothalamic mTOR signaling." (PMID 23056530, 2012). "As anorexia and hypermetabolism are common in cirrhosis, leptin levels may be increased in this disease." (PMID 15387890, 2004). "Furthermore, it is proposed that leptin might be more involved in elevating energy expenditure rather than merely decreasing food consumption in DEX-induced anorexia." (PMID 40900828, 2025). "Some studies also reported malnutrition in dialysis patients, with lower ghrelin levels in the dialysis group compared to the healthy group, and it was assumed that the low leptin levels were a consequence of protein–energy wasting (PEW) related to anorexia and not the cause of malnutrition." (PMID 40002759, 2025). "Additionally, anorexia-induced reductions in food and water intake may elevate leptin levels, subsequently contributing to testosterone reduction associated with spermatogenesis in male mice." (PMID 40118815, 2025). "In addition, the progression of anorexia in cachexia caused by LIF is partly influenced by leptin, which is a crucial adipokine, and changes in the adipose tissue or bodyweight can affect the leptin secretion." (PMID 35740622, 2022). "Thus, we sought to identify whether SPX action on leptin-induced anorexia is mediated via GALR2 and/or GALR3." (PMID 35204737, 2022). "Thus, leptin, one of the cytokines released in response to infection and inflammation, may directly affect the brain, such as inducing anorexia." (PMID 35886710, 2022). "Thus, the low leptin levels resulting from insufficient adipose tissue observed in anorexia may contribute to increased MAT and decreased bone formation." (PMID 27579023, 2016). "However, this inhibitory action of leptin on stress-induced anorexia could well represent an anxiolytic/antidepressant-like effect." (PMID 24624061, 2014). "While serum leptin is generally elevated in chronic kidney failure and hemodialysis patients, however, some other studies have not been shown to be a cause of uremia-related anorexia." (PMID 28197429, 2012). "CINV is associated with excessive secretion of motilin and anorexia is related to sustained elevation of leptin, suggesting the potential of these peptides as quantitative indicators of CINV and anorexia." (PMID 40045433, 2025). "This study comprehensively evaluated the changes in blood levels of five gastrointestinal peptide: substance P, neuropeptide (NPY), motilin, ghrelin and leptin, following chemotherapy, and the relationship between these peptides and CINV or anorexia." (PMID 40045433, 2025). "WAT-secreted leptin transmits body fat signals to the hypothalamus, activates POMC neurons, inhibits NPY/AgRP protein neurons, and contributes to anorexia behaviors." (PMID 39590824, 2024). "However, nesfatin-1 signaling may be important in mediating leptin-induced anorexia." (PMID 36904239, 2023). "However, it is still under debate whether leptin is a source of anorexia in ESRD patients." (PMID 30089153, 2018). "Activation of POMC/CART-expressing neurons by leptin results in release of α-MSH, which subsequently binds to melanocotin receptors (MCRs) and leads to anorexia and increased energy expenditure." (PMID 22518191, 2012). "Plasma level of leptin, an appetite-suppressing hormone, was significantly elevated on day 3, regardless of anorexia." (PMID 40045433, 2025). "Plasma leptin peaked significantly on day 3 in both anorexia and non-anorexia groups, and remained significantly higher on day 5 compared to baseline in anorexia group but not in non-anorexia group." (PMID 40045433, 2025).
Anorexia (continued). "Consequently, it seems most beneficial for future interventions to target CCK, leptin, PYY and insulin when investigating methods to augment energy intake to reduce the anorexia of ageing from an endocrine perspective." (PMID 31432431, 2020). "Hematocrit, insulin, ghrelin, and corticosterone levels did not resemble shifts typically observed in patients with anorexia, though decreases in leptin levels aligned with human reports." (PMID 31481515, 2019). "At the dose used, NVP-BSK805 did not have any effect on FI or BW, but blunted the anorexia and the decrease in BW induced by leptin." (PMID 29867515, 2018). "Some cachectic factors, such as cytokines, can inhibit the neuropeptide Y (NPY) pathway or imitate the negative feedback action of leptin on the hypothalamus, resulting in anorexia." (PMID 26843513, 2016). "As anorexia involves appetite-regulating hormones such as gut hormones (GLP-1, PYY, and ghrelin) and leptin, we further examined whether SJDBT affects their levels in serum." (PMID 24963216, 2014). "Serum leptin is generally elevated in end-stage kidney failure patients, but this has not been observed in anorexia." (PMID 28197430, 2012). "Serum leptin is generally elevated in hemodialysis, but this has not been shown to be related to anorexia." (PMID 28197429, 2012). "Taken together, our results suggest that in our cohort, leptin levels reflect fat mass depots, rather than independently contributing to uremic anorexia or modifying nutritional status and/or survival in chronic HD patients." (PMID 21676262, 2011). "Plasma leptin was significantly elevated on day 3 compared to baseline in both groups; the level remained significantly higher on day 5 compared to baseline in the anorexia group, but was not significantly different from baseline in the non-anorexia group." (PMID 40045433, 2025). "This was not due to TNF-induced anorexia or altered food consumption due to elevated leptin levels." (PMID 27045690, 2016). "It was thus not due to TNF-induced anorexia since TNF was genetically absent or to elevated leptin levels as has been hypothesized for human children with UC, since T/I mice ate more chow than their T/I-het littermates or WT mice." (PMID 27045690, 2016). "Given that leptin is still apparently absent from the chicken genome it is difficult to draw parallels at the regulatory level between these models of parasite‐induced anorexia and our own findings." (PMID 26017156, 2015). "Thus leptin levels reflect fat mass depots, rather than independently contributing to uremic anorexia or modifying nutritional status and/or survival in chronic hemodialysis patients." (PMID 21676262, 2011). "It is well-known that centrally applied Ucn2 elicits anorexia and hyperthermia via activation of the central CRH type 2 receptors We hypothesized that the responsiveness to Ucn2 changes during the course of aging, similarly to other catabolic mediators, such as leptin or alpha-MSH." (PMID 37240340, 2023). "Therefore, the role of leptin in anorexia–cachexia is not well established and is often speculated that the alterations in leptin levels may be in response to malnutrition and reduced fat mass rather than a consequence of elevated inflammatory cytokines." (PMID 33329046, 2020). "The small sample size may have resulted in insufficient statistical power to detect significant differences in plasma levels of peptides other than motilin and leptin between CINV and non-CINV groups, and between anorexia and non-anorexia groups." (PMID 40045433, 2025). "Furthermore, in mice lacking functional leptin (ob/ob) or leptin receptors (db/db), LIF-induced anorexia persisted without recovery." (PMID 35740622, 2022).
malnutrition (116 papers, 2004 to 2025). Inadequate nutrition resulting from poor diet, malabsorption, or abnormal nutrient distribution. "Malnutrition-induced changes in T-cell activity and metabolism are linked to changes in adipokine levels, most notably a drop in leptin, which has been demonstrated to be an invaluable intermediary between immunity and nutrition." (PMID 40507146, 2025). "Leptin also demonstrated the highest diagnostic accuracy for malnutrition among tested biomarkers (AUC = 0.69)." (PMID 41464844, 2025). "Energy deficit, malnutrition, or leptin deficiency suppresses BDNF and kisspeptin expression, resulting in delayed or absent pubertal progression." (PMID 41614834, 2025). "Children with severe malnutrition also have lower levels of the adipokine leptin, which have been reported to be associated with mortality in this context." (PMID 39028622, 2024). "It is suggested that, in malnutrition associated with cancer, leptin is not only an exponent of changes in the fat mass but is also an acute-phase reactant." (PMID 39337308, 2024). "Several studies have identified BMI, hemoglobin (HGB), total cholesterol (TC), albumin (ALB), and serum leptin as biomarkers associated with malnutrition in older individuals." (PMID 38622502, 2024). "Leptin is a signal of nutritional deficiency, and decreasing leptin levels trigger a range of responses, including restoring energy homeostasis by increasing food intake and reducing energy expenditure." (PMID 38553750, 2024). "In the case of the nutrition status assessment using the MNA score (malnutrition, at risk of malnutrition, adequate nutritional status), the parameters for which statistically significant differences were determined include leptin and resistin." (PMID 36978817, 2023). "Another possible cause for the association of leptin with a poor outcome in hemodialysis patients is malnutrition." (PMID 37189644, 2023). "The altered T cell function and metabolism seen in malnutrition are associated with altered adipokine levels, most particularly decreased leptin." (PMID 36678282, 2023). "ESRD is frequently associated with anorexia, malnutrition and hypervolemia, a setting that seems to correlate with leptin levels." (PMID 36289903, 2022). "An independent association between lower leptin levels and anemia was found, and in stage 5 CKD patients that were submitted to parathyroidectomy, increased leptin was associated with ameliorated anemia and malnutrition." (PMID 36289903, 2022). "In a study conducted on hemodialysis subjects, the deceased patients presented lower leptin values, which were associated with hypervolemia and malnutrition." (PMID 36289903, 2022). "Malnutrition also causes a decrease in adipocyte mass, resulting in a decrease in circulating leptin." (PMID 36143913, 2022). "Leptin deficiency or resistance is related to the imbalance of cytokine production, increased susceptibility to infection, autoimmune diseases, malnutrition, and inflammatory response." (PMID 35308138, 2022). "Lower levels of prealbumin, transferrin, IGF-1 and leptin are known to be associated with malnutrition and as expected, levels of these markers increased following nutritional intervention." (PMID 35334853, 2022). "Malnutrition causes a decrease in adipocyte mass, which results in a decrease in circulating leptin." (PMID 36143913, 2022). "Consistent with this, defective T cell activation and function occur upon leptin deficiency and in malnutrition, which can be rescued by leptin treatment in vitro or in vivo." (PMID 33927722, 2021). "Another study showed higher leptin levels in early postnatal malnutrition whereas malnutrition in two-month old rats was associated with decreased leptin blood levels." (PMID 32525953, 2020). "In fact, leptin-deficiency is associated with increased susceptibility to several infections, but moreover, certain infections also caused the downregulation of systemic leptin levels and mimic a malnutrition like situation." (PMID 32824322, 2020).
malnutrition (continued). "Low serum levels of leptin have been linked to severe malnutrition, acceleration of brain aging, and higher risk to develop AD." (PMID 31057368, 2019). "Accordingly, patients with malnutrition and consecutive low levels of leptin suffer from an increased susceptibility for severe infections including leishmaniosis and amiobiasis due to impaired T and NK cell functions." (PMID 31822667, 2019). "Mechanisms underlying the malnutrition-inflammation complex include the leptin/melanocortin signaling pathway and the direct effect of pro-inflammatory cytokines on muscle catabolism, as demonstrated in animal studies." (PMID 30155452, 2018). "Malnutrition or loss of appetite is a common characteristic of many infectious diseases including parasitic infections which result in reduced serum leptin levels." (PMID 30534129, 2018). "There is a need for studying the role of leptin in controlling parasitic infections since preponderance of such infections is associated with malnutrition which goes hand in hand in developing countries." (PMID 30534129, 2018). "At the same time, certain infections also caused the downregulation of systemic leptin levels and mimics malnutrition like situation." (PMID 29868503, 2018). "Emerging data from animal models and human indicates that immune dysfunction underlies the etiology of malnutrition and reduced immune-mediated protection from infections, which interplay between nutrition, leptin levels and immune responses." (PMID 30534129, 2018). "Logistic regression analysis revealed that INR and log-transformed leptin were independently associated with malnutrition." (PMID 27583675, 2016). "We propose that serum leptin should be further investigated as a potential biomarker for cirrhosis-associated malnutrition to enable early diagnosis, quantification of severity of malnutrition and monitoring response to treatment." (PMID 27583675, 2016). "The pre-existing mass and function of white adipose tissue appear to play roles in the adaptation to, and recovery from, malnutrition because low levels of leptin and adiponectin at baseline were associated with subsequent mortality." (PMID 25050734, 2014). "Serum leptin was measured with enzyme-linked immunosorbent assay (ELISA) method with direct dbc kit and malnutrition laboratory parameters measured with standard laboratory methods, patients anthropometric parameters evaluated after hemodialysis." (PMID 20142915, 2008). "Nevertheless, pursuit of the leptin hypothesis introduced important new energy to the proposition that malnutrition-associated immune defences must be understood as part of a larger, regulated physiology." (PMID 38068780, 2023). "According to the “leptin hypothesis”, low concentrations of this hormone contribute decisively to the cell-mediated immune depression of malnutrition while, as an incidental benefit, reducing the risk of inflammatory autoimmune disease." (PMID 38068780, 2023). "Starvation and malnutrition are both associated with poverty and reduced leptin levels." (PMID 36985226, 2023). "A low leptin is related to malnutrition and an increased risk of infection." (PMID 36366398, 2022). "The association between sclerostin and an anorexigenic hormone such as leptin may indicate that sclerostin plays a role as a risk factor of developing malnutrition in CKD patients." (PMID 36675692, 2022). "Systemic circulating leptin deficiency in malnutrition is linked with colitis due to faulty development of cytokines, and leptin usually increases immune response by activating and proliferating Th1 cells and mediating the secretion of pro-inflammatory cytokines." (PMID 33800583, 2021). "The leptin deficiency present in malnutrition is correlated, through the deficient production of cytokines, with bacterial, viral and parasitic infections, such as pneumonia, flu, tuberculosis, sepsis, colitis, leishmaniasis, trypanosomiasis, amoebiasis, and malaria." (PMID 33907162, 2021).